FBXL8 (F-box and leucine rich repeat protein 8)
Description:
Substrate-recognition component of the SCF (SKP1-CUL1-F-box protein)-type E3 ubiquitin ligase complex.
Synonyms: FBL8
Tractability: No criterion of Open Targets' tractability assessment is met for any kind of drug.
Gene: Protein-coding gene on chromosome 16 (67,159,932 to 67,164,570, forward strand). Ensembl gene ENSG00000135722.
Subcellular location (Human Protein Atlas): Golgi apparatus
Pathways (Reactome):
Immune System: Antigen processing: Ubiquitination & Proteasome degradation
Metabolism of proteins: Neddylation
Gene Ontology:
Molecular function: protein binding
Biological process: SCF-dependent proteasomal ubiquitin-dependent protein catabolic process
Cellular component: cytosol
Genetic constraint (gnomAD): Loss-of-function variants: 15 observed, 6.89 expected, observed/expected ratio (o/e) 2.18. That is too few expected variants to judge how well the gene tolerates losing a copy. Missense variants: 565 observed, 419.94 expected, observed/expected ratio (o/e) 1.35, 90% interval 1.25 to 1.44. Synonymous variants: 271 observed, 198.91 expected, observed/expected ratio (o/e) 1.36, 90% interval 1.23 to 1.51.
Homologues: Orthologues: chimpanzee FBXL8 (99% identical), macaque FBXL8 (95% identical), dog FBXL8 (84% identical), rabbit FBXL8 (83% identical), pig FBXL8 (82% identical), mouse Fbxl8 (79% identical), rat Fbxl8 (78% identical), guinea pig FBXL8 (75% identical), zebrafish fbxl8 (39% identical), tropical clawed frog fbxl8 (37% identical).
Diseases named in the same sentence as FBXL8 in open-access papers:
FBXL8 is named in the same sentence as 14 diseases in open-access papers, as found by Europe PMC text mining. Sharing a sentence is not in itself a finding about the gene and the disease. The quoted sentences say what the papers report.
breast carcinoma (9 papers, 2005 to 2024). "To elucidate the mechanisms underlying the pathophysiological significance of FBXL8, we performed gene specific-siRNA knockdown of FBXL8 in breast carcinoma cells to assess the potential loss/gain-of-function." (PMID 32784654, 2020). "Fbxl8 is an E3 ubiquitin ligase with oncogenic functions in breast cancer but tumor suppressor functions in lymphoma." (PMID 39543396, 2024). "In vitro analysis of 1349 matched breast cancer tissues showed that FBXL8 promoted cell survival and tumourigenesis, and its level increased with BRCA progression." (PMID 36855778, 2023). "We found that amongst all 71 F-box family members, FBXL8, a novel F-box factor, was prominently upregulated in breast carcinoma tissues, compared to the corresponding paired normal tissues (FDR < 0.05)." (PMID 32784654, 2020). "Scatter plot illustrates quantitative differences in the expression levels of FBXL8 mRNA in individual clinical samples, with 3-fold increase in breast carcinoma (expressed in log2)." (PMID 32784654, 2020). "The same study also showed that FBXL8 may be a novel anti-apoptosis factor and was positively correlated with higher breast cancer stage." (PMID 35999641, 2022). "FBXL8 was significantly upregulated in human breast carcinoma tissues." (PMID 35884544, 2022). "Furthermore, our IHC staining of breast carcinoma tissues demonstrated a reciprocal profile of FBXL8 versus CCND2 and IRF5 with cancer advancement over stages I–III." (PMID 32784654, 2020). "FBXO1 was negatively regulated by the E3 ligase (FZR1) and the co-regulator of E3 ligase (FBXL8), which were known to play an oncogenic role in breast cancer, and FBXO1 could inhibit the expression of ribonucleotide reductase M2 (RRM2), a pro-tumorigenic protein." (PMID 35046938, 2021). "FBXL8 knockdown leads to the accumulation of CCND2 and IRF5 in breast cancer cells and inhibited tumour progression." (PMID 36855778, 2023). "Few studies on FBXL8 have been undertaken in CRC; however, this gene has been reported to be significantly upregulated in breast cancer, mirroring our analysis of the TCGA-COAD dataset." (PMID 35999641, 2022). "FBXL8 downregulation increased accumulation of CCND2 and IRF5 and reduced the cancer-promoting chemokines, modulated TME, leading to repressing tumor metastasis in breast cancer." (PMID 36733484, 2023). "Interestingly, among all 71 F-box family members, there are four F-boxes (FBXO43, FBXO15, FBXL8, and CCNF) with significantly upregulated mRNA levels in breast carcinoma tissues." (PMID 34201347, 2021). "We studied CBFA2T3, FANCA, FBXL8, LRRC29, TERF2 and TERF2IP, six potential breast cancer TSG candidate genes located on the long arm of chromosome 16, which is involved in LOH in more than 50% of breast cancer cases." (PMID 16280054, 2005).
lymphoma (2 papers, 2021 to 2024). A malignant (clonal) proliferation of B- lymphocytes or T- lymphocytes which involves the lymph nodes, bone marrow and/or extranodal sites. "Conversely, knockdown of Fbxl8 promoted lymphoma cell proliferation with upregulated cyclin D3 expression." (PMID 33122824, 2021). "Fbxl8 overexpression significantly suppressed lymphoma cell proliferation whereas Fbxl8ΔF promotes cell proliferation relative to GFP control." (PMID 33122824, 2021). "Together these results demonstrate that Fbxl8 functions as a tumor suppressor through degradation of cyclin D3 in lymphoma." (PMID 33122824, 2021). "Clinically, the expression of cyclin D3 is inversely correlated with the expression of Fbxl8 in lymphomas from human patients implicating Fbxl8 functions as a tumor suppressor." (PMID 33122824, 2021). "Normal lymph node tissues, spleen, tonsil, and lymphomas arrayed on slides (US Biomax, Inc.)were stained with cyclin D3 and Fbxl8 specific antibodies and IHC scores of each core were calculated." (PMID 33122824, 2021). "Patient samples with low, medium, or high expression of cyclin D3 have high, medium, or low expression of Fbxl8, respectively, underscoring Fbxl8 negatively regulates cyclin D3 expression in human lymphomas in a dose dependent manner." (PMID 33122824, 2021). "In summary, Fbxl8 regulates cell cycle progression and lymphoma cell proliferation through cyclin D3." (PMID 33122824, 2021). "Fbxl8 overexpression dramatically suppressed oncogene-induced transformation in vitro and lymphoma progression in vivo." (PMID 33122824, 2021). "This further suggested that cyclin D3-dependent kinase might be a novel therapeutic target in certain lymphomas that harbor low expression of Fbxl8 or high expression of cyclin D3." (PMID 33122824, 2021). "Because overexpression of cyclin D3 or mutation of D3 at Thr283 is frequently observed in Burkitt’s lymphoma and leukemia and c-Myc driven murine lymphomas, we further defined whether Fbxl8 has tumor suppressive function in hematopoietic cells." (PMID 33122824, 2021). "Thus, either loss of Fbxl8 or gain of a cyclin D3 mutation that stabilizes cyclin D3 protein level will accelerate cell cycle progression and lymphoma cell growth consistent Fbxl8 functioning as a tumor suppressor." (PMID 33122824, 2021). "Importantly, cyclin D3T283A, a non-phosphorylable mutant, rescued Fbxl8 overexpression mediated cell proliferation attenuation, indicating that Fbxl8-cyclin D3 axis plays a critical role in regulating lymphoma cell proliferation." (PMID 33122824, 2021). "Cyclin D3TA overcomes Fbxl8 mediated attenuation of lymphoma proliferation." (PMID 33122824, 2021). "This supports the notion that Fbxl8-cyclin D3 axis might be a potential novel biomarker to predict the efficacy of CDK4/6i in lymphomas." (PMID 33122824, 2021). "We finally tested whether Fbxl8 reduces lymphoma proliferation through degradation of cyclin D3." (PMID 33122824, 2021). "We further used a recently developed online tool to assess the lymphoma patients’ overall survival with gene expression, and observed that the low expression of Fbxl8 mRNA significantly correlated with reduced overall survival for lymphoma patients while the expression of cyclin D3 mRNA does not." (PMID 33122824, 2021).
Burkitt lymphoma (1 paper, 2021). A rare form of malignant mature B-cell non-Hodgkin lymphoma. "Because cyclin D3T283 mutations co-occur coordinately with c-myc translocation in Burkitt’s lymphoma, we assessed Fbxl8 activity in the context of c-myc overexpression." (PMID 33122824, 2021). "We confirmed that Fbxl8 forms an SCF complex in vivo and in vitro and subsequently demonstrated that endogenous Fbxl8 binds to cyclin D3 in NIH3T3 cells and Burkitt’s lymphoma, Raji cells." (PMID 33122824, 2021).
colorectal cancer (1 paper, 2023). A primary or metastatic malignant neoplasm that affects the colon or rectum. "However, the regulation function and mechanism of FBXL8's involvement in colorectal cancer (CRC) remain unclear." (PMID 36855778, 2023).
colorectal tumour (1 paper, 2023). "•The up‐regulation of FBXL8 promoted the proliferation, invasion, migration and maintained the stem‐cell characteristics of colorectal tumour cells." (PMID 36855778, 2023). "The up‐regulation of FBXL8 promoted the proliferation, invasion and migration of CRC tumour cells and maintained the stem‐cell characteristics of colorectal tumour cells." (PMID 36855778, 2023).
heart failure (1 paper, 2024). Inability of the heart to pump blood at an adequate rate to meet tissue metabolic requirements. "The interaction of FBXL8-Snail1 in the heart may provide a promising therapy for preventing cardiac fibrosis and heart failure after MI." (PMID 38615011, 2024). "Although the E3 ubiquitin ligase FBXL8 is a key regulator in the cell cycle, cell proliferation, and inflammation, its role in post-MI ventricular fibrosis and heart failure remains unknown." (PMID 38615011, 2024). "Therefore, FBXL8 plays a crucial role in cardiac fibrosis and could be a potential therapeutic strategy for pro-fibrotic cardiac remodeling in heart failure patients." (PMID 38615011, 2024).
lung carcinoma (1 paper, 2022). "The function of ANKRD13B, FBXL8, and KBTBD12 in the carcinogenesis and progression of lung cancer need to be further investigated." (PMID 35884544, 2022).
Myocardial fibrosis (1 paper, 2024). "Masson’s trichrome-stained LV sections showed that myocardial fibrosis induced by MI was dramatically attenuated in FBXL8 overexpression rats compared with MI-NC rats, exhibited a smaller scar area and thicker infarcted wall thickness." (PMID 38615011, 2024). "Moreover, gene therapy of FBXL8 overexpression targeting CFs significantly attenuated myocardial fibrosis after MI." (PMID 38615011, 2024).
tumor (9 papers, 2005 to 2024). "Loss of Fbxl8 results in c-myc accumulation and cell cycle dysregulation, revealing tumor suppressor potential." (PMID 35438057, 2022). "Loss of Fbxl8 results in cyclin D3 accumulation, cell cycle dysregulation and oncogene-driven transformation revealing tumor suppressor potential." (PMID 33122824, 2021). "While correlative, this is consistent with the role of Fbxl8 as an antagonist of key tumor drivers and suggests that its loss may in fact contribute to tumor progression." (PMID 35438057, 2022). "CRC mouse xenograft tumour model confirmed that FBXL8 gene knockout inhibited tumour formation and liver metastasis." (PMID 36855778, 2023). "FBXL8 was found to interact with two tumour suppressors, cyclin D2 (CCND2) and interferon regulatory factor 5 (IRF5)." (PMID 36855778, 2023). "Knockout of FBXL8 down‐regulated the proliferation, migration and stem‐like properties of tumour cells." (PMID 36855778, 2023). "Based on the TIMER database, we analysed that FBXL8 was expressed in a variety of tumours, including CRC, and the expression of FBXL8 in CRC was significantly increased." (PMID 36855778, 2023). "The tumour volume and tumour weight were reduced in the FBXL8 KO group compared to the FBXL8 WT group." (PMID 36855778, 2023). "FBXL8 knockout HT29 cells were injected into the spleen of mice to establish tumour metastasis model." (PMID 36855778, 2023). "FBXL8 is a conserved F‐box protein, belonging to the ubiquitin ligase complex, which promotes the development and progression of tumours." (PMID 36855778, 2023). "Transformation assays revealed that c-Myc-driven transformation was suppressed by Fbxl8 and enhanced by Fbxl8ΔF, suggesting tumor suppressive function of Fbxl8." (PMID 33122824, 2021). "CA46 cells with Fbxl8 overexpression formed tumors slower than cells expressing GFP and cells expressing Fbxl8ΔF developed tumors faster than cells expressing GFP, indicating tumor suppressive function of Fbxl8 and consistent with cell growth curve." (PMID 33122824, 2021). "While cells expressing c-Myc accumulated through 5 rounds consistent with transformation, co-expression with Fbxl8 inhibited colony formation driven by c-Myc, indicating Fbxl8 is a tumor suppressor." (PMID 33122824, 2021). "Immune compromised mice injected with CA46 cells expressing GFP, Fbxl8, or Fbxl8ΔF were monitored every 2 days for tumor progressoin." (PMID 33122824, 2021). "We suggest this is consistent with our conclusions that Fbxl8 regulates cyclin D3 at posttranslational level and Fbxl8 has a tumor suppressive function." (PMID 33122824, 2021). "FBXL8 was found to interact with two tumor-suppressors, CCND2 (cyclin D2) and IRF5 (interferon regulatory factor 5)." (PMID 32784654, 2020). "In addition, FBXL8 knockout also decreased the tumour cell colony formation and inhibited the cell migration and invasion, as well as down‐regulated the expression of stem‐cell‐related indicators, whereas 53 knockout had the opposite effects." (PMID 36855778, 2023). "In vivo study showed that FBXL8 knockout inhibited the CRC tumour growth in mice." (PMID 36855778, 2023). "FBXL8 plays an important role in the pathological mechanism of a few tumours." (PMID 36855778, 2023). "Data thus far suggest a hypothesis wherein Fbxl8 should exhibit tumor suppressive properties reflecting its ability to antagonize cyclin D3." (PMID 33122824, 2021). "Additionally, NT-3, which was concomitantly decreased by knockdown of FBXL8, has been reported to modulate the tumor microenvironment to promote breast-to-brain metastasis." (PMID 32784654, 2020). "For example, FBXL8 showed significantly higher expression in both colon organoids of FAP versus healthy subjects and in TCGA-COAD tumor versus NAT." (PMID 35999641, 2022). "Co-IP study suggests that two tumor-suppressors, CCND2 and IRF5 are part of the immune-complex of FBXL8." (PMID 32784654, 2020).
tumor (continued). "Importantly, both FBXL8 and TRIM31-AS1 were also significantly differentially expressed in TCGA-COAD tumor versus matched NAT, supporting a role for these genes in CRC tumor development." (PMID 35999641, 2022). "Therefore, in the future, it would be interesting to design anti-BRCA strategies by counterbalancing the activities of E2 and E3 ligases, for example, to maintain CCNF to suppress tumor-promoter RRM2 and/or inhibit FBXL8 and FZR1 to reduce their targeting of tumor-suppressor CCNF protein." (PMID 34201347, 2021). "Possible candidates CBFA2T3, TERF2 and TERF2IP, FBXL8 and LRRC29 and FANCA were studied for insertion and deletion mutations and for expression differences using quantitative RT-PCR in a panel of tumour cell lines and primary tumours with and without loss of 16q." (PMID 16280054, 2005).
cancer (7 papers, 2020 to 2024). A tumor composed of atypical neoplastic, often pleomorphic cells that invade other tissues. "Knockdown of FBXL8 caused the accumulation of two cancer suppressors (CCND2, IRF5), which inhibited BRCA progression." (PMID 34201347, 2021). "We showed a novel molecular mechanism underlying the specific interaction of the pro-tumorigenic FBXL8 with two cancer suppressors, CCND2 and IRF5, resulting in their downregulation." (PMID 32784654, 2020). "Overexpression of Fbxo9 significantly reduced cancer cell migration compared with the overexpression of Fbxl3, Fbxl5, or Fbxl8." (PMID 38486234, 2024). "Thus, FBXL8 appears rather promiscuous, associating with multiple binding partners, to plausibly promote cancer formation and progression through the turnover of: (i) cell-cycle associated proteins, (ii) cancer- suppressors and (iii) proteins responsible for DNA repair/replication." (PMID 32784654, 2020). "Congruent to these findings, knockdown of FBXL8 significantly down-regulated cancer-promoting cytokines and chemokines." (PMID 32784654, 2020). "Of significance is that FBXL8 is a specific protein degradation enzyme which selectively targets cancer suppressors like CCND2 and IRF5." (PMID 32784654, 2020). "By ex vivo characterization of the “signature profile” of F-box factors in patients’ BRCA tissues, we identified for the first time, a novel F-Box factor, FBXL8, which was significantly upregulated with cancer advancement." (PMID 32784654, 2020). "Compared to normal control tissues, the mRNA level of FBXL8 in carcinoma tissues was significantly upregulated by up to 7.5-fold (*, False Discovery Rate, FDR < 0.05)." (PMID 32784654, 2020). "While we did not observe a high frequency of recurrent mutations in Fbxl8, we noted that expression of Fbxl8 was significantly reduced in a number of cancers." (PMID 35438057, 2022). "Thus, we propose that CCNF plays a cancer suppressor role, but its protein level is downmodulated in the disease, probably via FBXL8/FZR1-mediated degradation." (PMID 34201347, 2021). "While FBXL8 promotes cancer growth/metastasis, CCND2 and IRF5 suppress cancer progression." (PMID 32784654, 2020). "Since IRF-5 has been reported to stimulate inflammatory genes, the involvement of IRF5 indicates how FBXL8 might indirectly influence the cytokine profiles, hence promoting a pro-inflammatory cytokine-rich cancer microenvironment, as our results alluded to." (PMID 32784654, 2020). "Knockdown of FBXL8 and FBXO43 reduced cancer cell viability and proliferation, suggesting their pro-tumorigenic roles." (PMID 34201347, 2021). "Similar to FBXL8, the knockdown of FBXO43 reduced cancer cell viability and proliferation, suggesting its pro-tumorigenic role." (PMID 34201347, 2021). "In this study, we retrospectively profiled the transcriptome of BRCA tissues and found a notable upregulation of four SCFF-box E3 ligases (FBXL8, FBXO43, FBXO15, and CCNF) in the carcinoma tissues." (PMID 34201347, 2021). "Knockdown of FBXL8 in BRCA cells resulted in the accumulation of CCND2 and IRF5, concomitant with cancer suppression." (PMID 32784654, 2020). "Altogether, our computer modeling prediction and retrospective studies highlight the potential role of FBXL8 E3 ligase in specific degradation of CCND2 and IRF5 proteins as cancer progresses." (PMID 32784654, 2020). "We next investigated whether anti-cancer CCND2 and IRF5 are binding partners of FBXL8, with a view to providing explanations on how their interactions might impact BRCA progression." (PMID 32784654, 2020). "The expression of both the mRNA and protein of FBXL8 in BRCA tissues were consistently increased by up to 4-fold compared to normal tissues, and the levels in BRCA tissues were found to elevate with the advancement of cancer (p < 0.001)." (PMID 32784654, 2020).
cancer (continued). "Furthermore, we showed that knockdown of FBXL8 induced intrinsic apoptosis of the BRCA cells, suggesting that FBXL8 promotes BRCA advancement, as supported by the involvement of other F-box proteins in regulating the EMT process in cancers." (PMID 32784654, 2020). "Notably, among the predicted list of FBXL8-binding factors, two cancer suppressors, Cyclin D2 (CCND2) and Interferon Regulatory Factor 5 (IRF5), emerged prominently as potential interaction partners of FBXL8." (PMID 32784654, 2020). "Further investigation of Caspase activity showed that both Caspases-9 and -3 were activated in FBXL8 knocked down cells, indicating that the presence/increase in FBXL8 prevents intrinsic apoptosis and confers survival advantage to BRCA, hence favoring cancer progression." (PMID 32784654, 2020).
FBXL8 also shares sentences with these, for which no sentence is quoted: leukemia (1 paper); liver cancer (1); myocardial infarction (1); Pancreatic Cancer (1).